HTT (huntingtin)
Description:
[Huntingtin]: May play a role in microtubule-mediated transport or vesicle function. [Huntingtin, myristoylated N-terminal fragment]: Promotes the formation of autophagic vesicles.
Synonyms: HD; IT15; LOMARS
Tractability: Small molecule: a structure with a bound ligand is known; a high-quality ligand is known; it has a high-quality binding pocket; it belongs to a druggable protein family. PROTAC: it is named in the literature on targeted protein degradation; UniProt records ubiquitination sites on it; ubiquitination databases record sites on it; its protein half-life has been measured; a small molecule that binds it is known.
Chemical probes: ML168
Gene: Protein-coding gene on chromosome 4 (3,041,363 to 3,243,957, forward strand). Ensembl gene ENSG00000197386.
Subcellular location: Cytoplasm (Huntingtin); Nucleus; Early endosome; Cytoplasmic vesicle, autophagosome (Huntingtin, myristoylated N-terminal fragment)
Subcellular location (Human Protein Atlas): Nucleoplasm; Cytosol
Gene Ontology:
Molecular function: beta-tubulin binding; dynactin binding; dynein intermediate chain binding; heat shock protein binding; identical protein binding; kinase binding; phosphoprotein phosphatase activity; profilin binding; protein binding; transmembrane transporter binding
Biological process: establishment of mitotic spindle orientation; Golgi organization; negative regulation of extrinsic apoptotic signaling pathway; positive regulation of aggrephagy; positive regulation of apoptotic process; positive regulation of calcium-mediated signaling; positive regulation of CAMKK-AMPK signaling cascade; positive regulation of cilium assembly; positive regulation of lipophagy; positive regulation of mitophagy; protein destabilization; regulation of CAMKK-AMPK signaling cascade; retrograde vesicle-mediated transport, Golgi to endoplasmic reticulum; vesicle transport along microtubule; vocal learning; central nervous system development; endosomal transport; neurogenesis; synaptic vesicle transport; microtubule-based process; negative regulation of apoptotic process; regulation of signal transduction
Cellular component: autophagosome; axon; centriole; cytoplasm; cytoplasmic vesicle membrane; cytosol; dendrite; early endosome; endoplasmic reticulum; Golgi apparatus; inclusion body; late endosome; nucleoplasm; nucleus; perinuclear region of cytoplasm; postsynaptic cytosol; presynaptic cytosol; protein-containing complex; cytoplasmic vesicle; synapse
Genetic constraint (gnomAD): Loss-of-function variants: 79 observed, 269.56 expected, observed/expected ratio (o/e) 0.29, 90% interval 0.24 to 0.35. The upper end of that interval is the gene's LOEUF score, 0.35, which puts it in group 1 of 6, group 1 being the genes least tolerant of losing a copy. Missense variants: 2,819 observed, 3,414.7 expected, observed/expected ratio (o/e) 0.83, 90% interval 0.8 to 0.85. Synonymous variants: 1,373 observed, 1,368.8 expected, observed/expected ratio (o/e) 1, 90% interval 0.96 to 1.05.
Gene-disease validity (ClinGen):
ClinGen rates the evidence that HTT causes each of these diseases.
Huntington disease (autosomal dominant): Definitive. Huntington disease (HD) is a rare neurodegenerative disorder of the central nervous system characterized by unwanted choreatic movements, behavioral and psychiatric disturbances and dementia.
Homologues: Orthologues: chimpanzee HTT (99% identical), macaque HTT (96% identical), rat Htt (91% identical), mouse Htt (91% identical), guinea pig HTT (90% identical), rabbit HTT (89% identical), pig HTT (88% identical), dog HTT (88% identical), tropical clawed frog htt (78% identical), zebrafish htt (72% identical), Drosophila melanogaster htt (23% identical), Caenorhabditis elegans F21G4.6 (14% identical).
Diseases named in the same sentence as HTT in open-access papers:
HTT is named in the same sentence as 178 diseases in open-access papers, as found by Europe PMC text mining. Sharing a sentence is not in itself a finding about the gene and the disease. The quoted sentences say what the papers report.
Huntington disease (2,050 papers, 2005 to 2026). "The hallmark of Huntington's disease is the accumulation of intraneuronal aggregates of mutant HTT protein and polyglutamine (polyQ)-containing fragments, which causes impaired proteostasis and is an important Huntington's disease therapeutic target." (PMID 41578740, 2026). "Huntington's disease (HD) is caused by expansion of the polyglutamine stretch in the widely expressed huntingtin (HTT) protein." (PMID 41648922, 2026). "Huntington's disease (HD) is a fatal neurodegenerative disease caused by an expanded polyglutamine (CAG) repeat in the N-terminal of the huntingtin protein (HTT)." (PMID 41926221, 2026). "Huntington’s disease (HD) is a hereditary neurodegenerative disorder caused by the expansion of CAG trinucleotide repeats within the huntingtin gene (HTT)." (PMID 41545439, 2026). "Huntington's disease, an autosomal dominantly inherited neurodegenerative disorder, involves mutations in the HTT gene, resulting in abnormal accumulation of Huntingtin protein, ultimately causing neuronal dysfunction and death." (PMID 41497405, 2026). "Aggregation of mutant huntingtin (mHTT) is a neurologic hallmark of Huntington disease (HD), a neurodegenerative disorder caused by the expansion of a cytosine-adenine-guanine repeat tract in the huntingtin gene (HTT)." (PMID 41233147, 2026). "Huntington's disease (HD) is caused by a CAG repeat expansion mutation in the Huntingtin (HTT) gene that transcribes into mRNA and translates into a polyglutamine tract." (PMID 41884622, 2026). "Huntington's disease (HD) is a rare autosomal dominant neurodegenerative disorder caused by expansion of the cytosine-adenine-guanine (CAG) trinucleotide repeat in the huntingtin (HTT) gene." (PMID 41755956, 2026). "Huntington's disease (HD) is a rare, inherited neurodegenerative disorder caused by mutations in the huntingtin (HTT) gene." (PMID 41608623, 2026). "Huntington's disease (HD) is a neurodegenerative disorder caused by the expansion of CAG repeats in the gene encoding huntingtin." (PMID 41729074, 2026). "Huntington's disease (HD) is a neurodegenerative autosomal dominant hereditary disease caused by a CAG triplet repeat expansion mutation in the gene encoding the huntingtin (HTT) protein." (PMID 42109206, 2026). "Huntington’s disease (HD) is caused by autosomal dominant mutations in the HTT gene on chromosome 4, resulting in abnormally expanded CAG repeats that encode polyglutamine chains in huntingtin (HTT) proteins." (PMID 41602154, 2026). "Huntington's disease (HD) is a neurodegenerative disorder caused by the expansion of the CAG trinucleotide in the exon 1 of the huntingtin gmodellerene." (PMID 42280266, 2026). "The strongest association was with a coding variant in HTT, the causal gene for Huntington’s disease." (PMID 41001472, 2025). "Huntington's disease (HD) is a neurodegenerative condition caused by CAG repeat expansions in the huntingtin (HTT) gene and characterized by amyloid‐like protein deposits in patients." (PMID 40702881, 2025). "Huntington’s disease (HD) is strongly associated with psychiatric symptoms, yet, associations between huntingtin gene (HTT) CAG repeat size variations and psychiatric phenotypes outside the HD complex are still under-investigated." (PMID 39572770, 2025). "Huntington’s disease (HD) is an autosomal dominant neurodegenerative disorder caused by a pathological expansion of CAG trinucleotide repeats in the huntingtin (HTT) gene on chromosome 4p16.3." (PMID 40725699, 2025). "Huntington's disease (HD) is a devastating neurodegenerative disorder caused by abnormal CAG trinucleotide repeat expansion in the gene huntingtin (HTT)." (PMID 41147161, 2025). "Huntington's disease (HD) is an autosomal dominant neurodegenerative disorder caused by an unstable expansion of the CAG repeat in the exon 1 of the huntingtin gene (HTT), which results in a mutated huntingtin protein (mHTT)." (PMID 40774881, 2025).
Huntington disease (continued). "CAG repeat expansions within the HTT gene cause Huntington's disease (HD), a devastating neurodegenerative disease characterized by progressive movement, cognitive, and behavioral symptoms." (PMID 40838126, 2025). "The CAG•CTG sequence is found in approximately one-third of pathogenic TNR loci, including the HTT gene that causes Huntington’s disease." (PMID 40419681, 2025). "Huntington’s disease (HD) is a triplet repeat disorder characterized by the expansion of a CAG tract in the huntingtin gene (HTT) that encodes an expanded polyglutamine motif." (PMID 40368883, 2025). "Huntington’s disease, which primarily affects the striatum, is characterized by mutant HTT gene expression, leading to neuronal loss and network dysfunction between the basal ganglia and thalamus." (PMID 41142949, 2025). "The HTT protein and its phosphorylation are closely linked in both normal neuronal physiology and Huntington’s disease (HD) pathology." (PMID 41303392, 2025). "Huntington’s disease is a progressive, untreatable neurodegenerative disorder caused by a mutation in the Huntingtin gene." (PMID 40244185, 2025). "Huntington’s Disease (HD) is caused by a CAG repeat expansion in the gene encoding huntingtin (HTT)." (PMID 40258535, 2025). "Huntington’s disease (HD) is a hereditary neurodegenerative disorder caused by expanded cytosine-adenine-guanine (CAG) repeats in the huntingtin (HTT) gene." (PMID 41446471, 2025). "Huntington's disease (HD) is another neurodegenerative disorder that stems from a mutation in the Huntingtin (HTT) gene, yet the precise mechanisms and HD development remain elusive." (PMID 40041912, 2025). "CAG repeat expansions in the HTT gene produce a toxic mutant huntingtin (mHTT) protein, therefore causing the monogenic neurodegenerative disease known as Huntington’s disease (HD)." (PMID 40430848, 2025). "Huntington's disease (HD) is a fatal dominant neurodegenerative disease caused by expansion of a glutamine-coding (polyQ) CAG tract near the 5′ end of the Huntingtin (HTT) gene." (PMID 40205980, 2025). "Huntington’s disease (HD) is caused by a CAG repeat expansion in the huntingtin (HTT) gene, resulting in an elongated polyglutamine tract in the protein." (PMID 39940966, 2025). "Huntington’s disease (HD) is an autosomal dominant neurodegenerative disease caused by an abnormal expansion of cytosine-adenine-guanosine (CAG) trinucleotidein the huntingtin gene." (PMID 40859407, 2025). "A CAG repeat expansion due to mutations in the HTT gene encoding huntingtin is responsible for the development of Huntington’s disease (HD), a progressive neurological disorder." (PMID 39963432, 2025). "Multi-epitope immunopurifications of huntingtin (HTT) from vulnerable brain regions of Huntington’s disease (HD) models identify disease-linked protein interaction networks, capturing HD cell biology across pathways and subcellular compartments." (PMID 40169779, 2025). "We focused on the huntingtin (HTT) gene in which an eCAGr in exon 1 causes Huntington’s disease, a progressive neurodegenerative disorder." (PMID 40842239, 2025). "Huntington’s disease is a dominant neurodegenerative disorder caused by the expansion of glutamine-encoding trinucleotide (CAG) repeats in exon 1 of the huntingtin gene (HTT)." (PMID 41511351, 2025). "Huntington’s disease (HD), also known as Huntington’s chorea, is an autosomal dominant neurodegenerative disorder characterized by the mutation of the huntingtin gene on chromosome 4." (PMID 40584038, 2025). "Huntington’s disease (HD) is an autosomal dominant neurodegenerative disorder caused by a trinucleotide repeat expansion in exon 1 of the huntingtin (HTT) gene." (PMID 40520366, 2025). "Huntington’s disease (HD) is an autosomal dominant neurodegenerative disorder caused by the abnormal expansion of CAG trinucleotide repeats in the Huntingtin (HTT) gene." (PMID 40564109, 2025).
Huntington disease (continued). "Huntington’s Disease is an autosomal dominant disease caused by expansion of tri-nucleotide repeats (CAG) in the N-terminal domain of the huntingtin (htt) gene, encoding the amino acid Q (glutamine)." (PMID 40969213, 2025). "Huntington's disease, characterized by the appearance of defective motor, cognitive, and behavioral traits, arises from a mutation in the huntingtin gene." (PMID 40123457, 2025). "Huntingtin (HTT) is the gene linked to Huntington’s disease (HD), a neurodegenerative disorder characterized by cognitive, motor and psychiatric disturbance." (PMID 40844528, 2025). "HTT1a was identified in human and mouse Huntington’s disease brain as the pathogenic exon 1 mRNA generated from aberrant splicing between exon 1 and 2 of HTT that contributes to aggregate formation and neuronal dysfunction." (PMID 40926977, 2025). "Huntington's disease is a fatal neurodegenerative disorder caused by expansion of CAG trinucleotide repeats in the Huntingtin (HTT) gene, leading to the inclusion of a polyglutamine (polyQ) tract in the encoded protein." (PMID 38949989, 2025). "Background/Objectives: Huntington’s disease (HD) is an autosomal dominant neurodegenerative disorder caused by a CAG nucleotide repeat expansion in the Huntingtin (HTT) gene." (PMID 41095675, 2025). "Misfolding and aggregation of huntingtin exon-1 (Httex1) with an expanded polyglutamine region is a key pathological hallmark of Huntington’s disease, making conformationally specific Httex1 binders potentially valuable diagnostic or therapeutic tools." (PMID 41391760, 2025). "Huntingtons Disease: Huntingtons Disease (HD) is a genetic neurodegenerative disorder caused by a mutation in the huntingtin gene, which leads to progressive cognitive decline, psychiatric symptoms, and involuntary movements." (PMID 40904731, 2025). "Huntington’s disease is a neurodegenerative disorder caused by an expanded CAG repeat mutation in the Huntingtin (HTT) gene." (PMID 39391934, 2025). "Huntington’s Disease (HD) is an autosomal dominant neurodegenerative disorder caused by the expansion of CAG trinucleotide repeats in the huntingtin (Htt) gene on chromosome 4." (PMID 40177520, 2025). "Huntington’s disease is a progressive neurodegenerative condition caused by poly-glutamine(Q) repeat expansion of Huntingtin (HTT) protein." (PMID 39172219, 2025). "Huntington disease’s (HD) is a neurodegenerative disorder caused by the expansion of a polyglutamine region (PolyQ) within the huntingtin protein (HTT)." (PMID 40358175, 2025). "Huntington’s disease (HD) is an autosomal dominant disorder caused by CAG trinucleotide expansions in the HTT gene that results in polyglutamine (polyQ)-expanded mutant huntingtin (mHTT) protein." (PMID 40778304, 2025). "Huntington’s disease (HD) is an autosomal dominant neurodegenerative disorder caused by the expansion of CAG repeats in the huntingtin gene (HTT)." (PMID 40635054, 2025). "Huntington’s disease (HD) is an autosomal dominant neurodegenerative disorder caused by CAG repeat expansions in exon-1 of the Huntingtin (HTT) gene, resulting in an elongated polyglutamine (polyQ) chain within the Huntingtin (Htt) protein." (PMID 40534869, 2025). "For instance, Huntington’s disease results from mutations in the huntingtin (HTT) gene, leading to an expanded polyglutamine (polyQ) repeat that is prone to aggregation." (PMID 40903652, 2025). "Huntington’s disease (HD) is a rare autosomal dominant disorder caused by a genetic mutation in the huntingtin gene." (PMID 40913168, 2025). "Huntington’s disease (HD) is a hereditary neurodegenerative disease inherited as an autosomal dominant trait caused by the expansion of the CAG repeat in the huntingtin (HTT) gene." (PMID 40123457, 2025). "Huntington's disease (HD) is a neurodegenerative disorder caused by a CAG repeat expansion in the HTT gene encoding a mutant huntingtin (mHtt) protein." (PMID 39592326, 2025).
Huntington disease (continued). "Huntington's disease (HD) is a neurodegenerative disorder caused by a mutation in the huntingtin (HTT) gene, typically involving an expansion of CAG trinucleotide repeats." (PMID 41211267, 2025). "An expanded CAG repeat in the huntingtin gene (HTT) causes Huntington’s disease (HD), a fatal neurodegenerative disease for which there is currently no cure." (PMID 40748251, 2025). "Huntington’s disease (HD) is an autosomal dominant neurodegenerative disease caused by CAG repeat expansion in the huntingtin gene, with mutant huntingtin expression." (PMID 40457034, 2025). "Huntington’s disease (HD) is a neurodegenerative disorder caused by CAG trinucleotides expansion on chromosome 4 resulting in the production of mutant Huntingtin (mHtt)." (PMID 39891767, 2025). "Huntington’s disease (HD) is an autosomal dominant disorder caused by the abnormal expansion of the polyglutamine (polyQ) tract in the huntingtin protein (HTT), which leads to the formation of inclusion bodies in neurons." (PMID 41551612, 2025). "Huntington’s disease (HD) is a neurodegenerative autosomal inherit disorder caused by the CAG repeat expansion in the huntingtin gene (HTT)." (PMID 41415912, 2025). "Background/Objectives: Huntington’s disease (HD) is an autosomal dominant neurodegenerative disorder caused by the expansion of the CAG nucleotide repeat in the first exon of the huntingtin (HTT) gene." (PMID 40002561, 2025). "Huntington’s disease (HD) is another neurodegenerative disorder caused by huntingtin (HTT) protein (3144 amino acids) aggregation in human brain nerve cells." (PMID 41303502, 2025). "Huntington’s disease (HD) is a fatal neurodegenerative disorder caused by inheriting an expanded CAG repeat tract in the huntingtin gene (HTT) that further expands in somatic cells over an individual’s lifetime." (PMID 40791503, 2025). "Huntington’s disease (HD) is caused by the expansion of the polyglutamine stretch in huntingtin protein (HTT) resulting in hallmark aggresomes/inclusion bodies (IBs) composed of mutant huntingtin protein (mHTT) and its fragments." (PMID 40392702, 2025). "Huntington’s disease (HD) is a progressive neurodegenerative condition caused by the expansion of the polyglutamine (polyQ) region in the huntingtin (Htt) protein." (PMID 40510202, 2025). "Huntington’s disease (HD) is an autosomal dominant neurodegenerative disorder caused by the expansion of the CAG nucleotide repeat in the first exon of the huntingtin (HTT) gene." (PMID 40002561, 2025). "Huntington’s disease (HD) is a progressive neurodegenerative disorder caused by an autosomal dominant inheritance of an expanded CAG repeat in exon 1 of the huntingtin (HTT) gene." (PMID 41281562, 2025). "Huntington’s disease (HD) is caused by CAG repeat expansions in the huntingtin (HTT) gene, producing a mutant protein (mHTT) that forms aggregates." (PMID 40940752, 2025). "Huntington's disease (HD) is an autosomal dominant neurodegenerative disorder caused by an expanded CAG repeat within the HTT gene, leading to an elongated polyglutamine tract in the huntingtin protein." (PMID 40772422, 2025). "Huntington's disease (HD) is a monogenic autosomal dominant disease caused by a mutation in the gene that codes for huntingtin protein (HTT)." (PMID 40827215, 2025). "Huntington’s disease (HD) is a progressive neurodegenerative disease resulting from a mutation in the huntingtin (HTT) gene and characterized by progressive motor dysfunction, cognitive decline, and psychiatric disturbances." (PMID 39751928, 2025). "Multi-epitope immunopurifications of huntingtin (HTT) from vulnerable brain regions of Huntington’s disease (HD) models identify disease-linked protein interactions networks, capturing HD cell biology across pathways and subcellular compartments." (PMID 40169779, 2025).